BECN1 (beclin 1)
Diseases named in the same sentence as BECN1 in open-access papers (continued):
Sharing a sentence is not in itself a finding about the gene and the disease.
Hypertension (5 papers, 2016 to 2021). The presence of chronic increased pressure in the systemic arterial system. "HSD increased the levels of LC3 II/LC3 I, Beclin-1, and ATG7 in the heart of rats with hypertension and non-hypertension." (PMID 33996809, 2021). "The levels of cleaved-caspase 3/caspase 3, cleaved-caspase 8/caspase 8, Bax/Bcl2, LC3 II/LC3 I, Beclin-1 and autophagy related 7 (ATG7) were increased in the heart of HSD rats with hypertension (HTN), and in hypertension-prone (HP) and hypertension-resistant (HR) rats." (PMID 33996809, 2021).
inflammatory bowel disease (5 papers, 2012 to 2026). A spectrum of small and large bowel inflammatory diseases of unknown etiology. "The interaction of autophagy proteins, which also include BECN1, L-chain microtubule-associated protein 3 (LC3/LC3-II) and autophagy-related (ATG) protein 5 (ATG5) with inflammatory bowel disease (IBD) susceptibility genes is discussed." (PMID 36835075, 2023).
invasive breast carcinoma (5 papers, 2014 to 2021). A carcinoma that infiltrates the breast parenchyma. "Indeed, the expression of BECN1 (Beclin 1) is frequently inactivated by a loss of heterozygosity (LOH) combined with a promoter hypermethylation in invasive breast cancers." (PMID 31861179, 2019). "A higher TFEB and Beclin-1 expression correlate with shorter survival in patients with chemo-treated invasive breast cancer (respectively HR 3.46, CI.95 1.27–9.47, p < 0.05 and 7.11, CI.95 2.54–19.9)." (PMID 34663249, 2021). "In previous studies on invasive breast cancers, expression of autophagy-related proteins such as LC3A, LC3B, and beclin-1 was shown to be associated with ER negativity and PR negativity." (PMID 25140630, 2014).
periodontitis (5 papers, 2017 to 2025). An acute or chronic inflammatory process that affects the tissues that surround and support the teeth. "Mid-term research (2011–2017), with key keywords: cell cycle, Beclin 1, inflammation, osteogenic differentiation, periodontitis, oxidative stress, mesenchymal stem cells, pathway, NF-κB." (PMID 40417676, 2025). "For example, compared with healthy people, the expression levels of ATGs such as LC3, Beclin-1, Atg7, and Atg12 are higher in periodontal ligament tissue cells (PDLSCs) of periodontitis patients." (PMID 35846745, 2022). "Several studies have outlined the relevance of Beclin 1 in periodontitis." (PMID 32971808, 2020). "The result showed that the expression of LC3, Beclin-1, and MREG in periodontitis was less than that in healthy people." (PMID 35846745, 2022). "Specifically, there were higher protein expression levels of LC3II/I and Beclin 1, as well as increased transcriptional levels of LC3, Beclin-1, Atg7, and Atg12, in periodontal ligament stem cells isolated from patients with periodontitis compared with healthy individuals." (PMID 28690552, 2017).
pulmonary hypertension (5 papers, 2017 to 2024). Increased pressure within the pulmonary circulation due to lung or heart disorder. "Meanwhile, Glucagon-like peptide 1 receptor agonists attenuate autophagy via Drp1/NOX- and Atg-5/Atg-7/Beclin-1/LC3β pathways to improve pulmonary hypertension." (PMID 37491292, 2023). "In a mouse model of pulmonary hypertension, elevated levels of beclin-1 and autophagy (LC3-II protein levels and autophagic vacuoles) coincided with significantly worse cardiac function." (PMID 36531941, 2022).
rectal cancer (5 papers, 2014 to 2025). A primary or metastatic malignant neoplasm that affects the rectum. "We also did not measure expression of other autophagy proteins, such as p62 and Beclin-1, which were previously reported to have prognostic value for colon and rectal cancers." (PMID 40361494, 2025). "In 96 cases of rectal carcinoma, increased beclin-1 expression predicted a significantly reduced pathological response (macroscopic versus microscopic or no residual tumor) to chemoradiation (high: 14.2 % vs. low: 40 %; P = 0.017)." (PMID 26965179, 2016). "Thus, the aim of the present study was to clarify the clinical role of the expression of autophagy-related proteins (beclin-1 and LC3β) in the neoadjuvant setting for rectal cancer." (PMID 26965179, 2016). "The small sample size, small diagnostic tissue samples, and retrospective nature of the present study might not reflect the biological properties of the entire population with rectal cancer and does not allow us to draw conclusions regarding the prognostic value of LC3β or beclin-1 in rectal cancer." (PMID 26965179, 2016).
retinal degeneration (5 papers, 2020 to 2022). Degeneration of the retina. "Surprisingly, Becn1-Het mice experienced the same extent of retinal degeneration as was observed in wild-type mice, following an intravitreal injection of a chemical proteasome inhibitor." (PMID 34298888, 2021). "To extend our findings to other types of retinal degeneration models, we asked if excitotoxicity- and neuroinflammation-induced RGC death could be modified in Becn1-Het mice." (PMID 34298888, 2021). "Similar to the retinal degeneration induced by MG-262 and tunicamycin IVT injection, we did not observe any statistically significant difference in the retinal structural changes and reduction in Nefl gene expression upon IVT injection of NMDA or LPS between WT and Becn1-Het mice." (PMID 34298888, 2021).
silicosis (5 papers, 2017 to 2025). Silicosis is a respiratory disease caused by breathing in (inhaling) silica dust. "Therefore, we explored the involvement of autophagy in the effects of metformin on silicosis by assessing the expression of p62, Beclin 1 and LC3." (PMID 34434111, 2021). "Furthermore, the expression of LC3BII and BECN1, two autophagic markers, were also increased in macrophages from the BALF of silicosis patients." (PMID 28277537, 2017).
steatosis (5 papers, 2016 to 2023). Increased lipid within the cytoplasm of cells. "In contrast, Compound C decreased the levels of TET2, ATG5, and Beclin-1 and increased p62 in the hepatocyte steatosis model." (PMID 33551821, 2020). "In our study, empagliflozin treatment led to activation of autophagy in both db/db mice and a hepatocyte steatosis model, based on alterations of autophagy markers including p62, Beclin-1, and ATG5." (PMID 33551821, 2020). "The expression scores of LC3 (r=−0.62, P<0.05) and Beclin-1 (r=−0.54, P<0.05) were inversely correlated with the percentages of steatosis." (PMID 27077802, 2016). "Immunofluorescence and western blot results showed that under PA and HG-induced steatosis, cellular levels of ATG5 and Beclin-1 were decreased, and p62 was increased." (PMID 33551821, 2020). "Resveratrol (a pharmacological SIRT1 activator) significantly prevented hepatocyte ballooning and steatosis, along with the changed levels of LC3-II, Beclin 1, and P62, as well as ER stress." (PMID 32477116, 2020). "To investigate the effects of steatosis on hepatocellular autophagy during I/R, we examined liver LC3 and Beclin-1 expression by western blotting at 6 h of reperfusion." (PMID 27077802, 2016). "The present results showed a decrease in the expression of Beclin-1, PINK1, Parkin, LC3-I, and LC3-II in both the FLHS hens and steatosis hepatic cells, indicating that the autophagy scavenging mechanism was weakened by steatosis in the hepatic cells." (PMID 37373507, 2023). "Also, under the depletion of TET2, autophagy was no longer activated by empagliflozin in the hepatocyte steatosis model, based on the levels of Beclin-1, ATG5, and p62." (PMID 33551821, 2020).
T-cell lymphoma (5 papers, 2011 to 2025). "Surprisingly, Beclin 1+/− did not significantly promote T-cell lymphoma formation in Lck-Bax38/1 mice." (PMID 21611191, 2011). "However, Casp9DN did not significantly accelerate T-cell lymphoma alone, or in combination with Lck-Bax38/1, or with Beclin 1+/− mice, two tumor-prone strains in which altered mitochondrial function has been implicated in promoting tumor development." (PMID 21611191, 2011).
acute lymphoblastic leukemia (4 papers, 2015 to 2024). Leukemia with an acute onset, characterized by the presence of lymphoblasts in the bone marrow and the peripheral blood. "The evidence highlights a critical linkage between Beclin-1-mediated autophagy and the efficacy of therapeutic agents in acute lymphoblastic leukemia (ALL), particularly influencing drug tolerance." (PMID 38887520, 2024). "A report has stated that in AML and acute lymphoblastic leukemia, Beclin-1 expression was considerably reduced in comparison to controls and that reduced Beclin-1 gene expression was correlated with minor survival." (PMID 33704184, 2020). "Indeed, in acute lymphoblastic leukemia (ALL), obatoclax provokes disruption of the interaction between MCL1 and BECN1, inactivation of MTOR, and activation of the necroptotic cell death." (PMID 34830777, 2021).
adenomyosis (4 papers, 2018 to 2024). The growth of endometrial tissue inside the muscular wall of the uterine corpus. "Ren has previously revealed downregulation of Beclin-1 in both eutopic endometrium and foci of adenomyosis, which were in accordance with ours." (PMID 35768796, 2022). "We further detected abnormally decreased expression of autophagy markers (LC3-B/LC3-A and Beclin-1) in the endometria of adenomyosis patients and their expression levels weremoderately positively correlated with KLF4 expression levels." (PMID 35761172, 2022). "Similar to the endometrial samples of adenomyosis patients, we detected abnormally decreased expression of KLF4 and autophagy markers (LC3-B/LC3-A and Beclin-1) in the uteri of adenomyosis mice." (PMID 35761172, 2022). "Moreover, Beclin-1 protein expression was negatively correlated with the serum levels of CA-125 and pelvic pain, indicating that there is a certain relationship between autophagy and the occurrence and development of uterine adenomyosis." (PMID 29992166, 2018). "Endometrial tissues from adenomyosis patients and uteri from an adenomyosis mouse model were collected for the detection of different expression patterns of KLF4 and autophagy markers (LC3-B/LC3-A and Beclin-1) compared with control groups." (PMID 35761172, 2022). "Contrary to the expression pattern of KLF4, we found that the autophagy levels of endometrial stromal cells were significantly lower in infertile women with adenomyosis (decreased expression of LC3-B/LC3-A and Beclin-1) than in fertile women, similar to other studies." (PMID 35761172, 2022). "Therefore, the expression of KLF4 and the autophagy markers LC3-B/LC3-A and Beclin-1 was abnormally decreased in the endometria of adenomyosis patients, and there was a moderate positive correlation between KLF4 and autophagy markers (LC3-B/LC3-A and Beclin-1)." (PMID 35761172, 2022). "Furthermore, immunohistochemical analysis showed that the expression levels of KLF4, LC3-B and Beclin-1 in endometrial stromal cells of patients with adenomyosis were significantly decreased, while LC3-A levels were not decreased." (PMID 35761172, 2022). "Researchers have compared 30 cases of adenomyosis in eutopic endometrium with endometrial tissues from 32 normal women, revealing that the Beclin-1 mRNA and protein expression levels were obviously reduced in the diseased tissues compared to the normal controls." (PMID 29992166, 2018).
B cell lymphoma (4 papers, 2011 to 2022). "Furthermore, it was reported that Beclin-1-deficient mice had a high risk of developing spontaneous precursor B-cell lymphoma, evidencing a key role of Beclin-1 and autophagy in normal cell maintenance." (PMID 36291856, 2022).
Barrett esophagus (4 papers, 2018 to 2022). Esophageal lesion lined with columnar metaplastic epithelium which is flat or villiform. "Beclin-1 expression was high in normal esophageal epithelium and HET-1A cells (derived from normal squamous epithelium) but low in Barrett’s esophagus and esophageal adenocarcinoma cell lines (CP-A, CP-C, and OE33)." (PMID 35806184, 2022). "Lower levels of the early autophagy initiator Beclin 1 was reported in dysplastic Barrett’s esophagus and EAC, when compared to non-dysplastic Barrett’s esophagus and non-neoplastic mucosa." (PMID 29897944, 2018).
chronic hepatitis (4 papers, 2012 to 2021). An active inflammatory process affecting the liver for more than six months. "The reported increase Beclin-1 in chronic hepatitis as documented by Al-Shenawy (2016), could be a body defense mechanism to prevent the progression towards carcinogenesis." (PMID 33906303, 2021). "Consequently, a suggested role of autophagy in chronic hepatitis progression rather than HCC occurrence which was mainly linked to the suppressor function of Beclin-1." (PMID 33906303, 2021). "In HBV transgenic mice, heterozygous deletion of BECLIN 1 increases frequency of spontaneous malignancies and accelerated the onset of HCC; in line with this, the expression levels of BECLIN 1 mRNA is lower in human HCC tissue than in chronic hepatitis tissue." (PMID 32181249, 2020).
cognitive decline (4 papers, 2015 to 2025). "For instance, augmenting Beclin-1 expression in Becn1F121A/F121A mice has been shown to mitigate memory loss and cognitive decline induced by Aβ and Tau." (PMID 38003724, 2023).
colorectal tumor (4 papers, 2016 to 2022). "It has been shown in human colorectal tumors that overexpression of Beclin-1 determines a poor prognosis factor with lower efficacy of chemotherapy." (PMID 36361753, 2022). "This study provides evidence that BRAF oncogene induces the expression of key autophagic markers, like LC3 and BECN1 in colorectal tumor cells." (PMID 26802026, 2016). "Level of BECLIN 1, a key positive regulator of autophagy that initiates autophagosome formation, was recently shown to be inversely correlated with the quantity of F. nucleatum in colorectal tumors." (PMID 33923277, 2021).
dental fluorosis (4 papers, 2018 to 2023). A condition that results from excessive fluoride ingestion during tooth development, resulting in tooth discoloration ranging from white streaks to brown stains and cracks or pits in the tooth enamel. "The question of how autophagy changes in osteoblasts under the action of a low dose of fluoride was then raised, and the study tested the changes in autophagy-related genes LC3A and Beclin 1 to explore the relationship between fluorosis and autophagy." (PMID 34276389, 2021). "The present study analyzes the key factors related to autophagy (LC3A and Beclin 1) and apoptosis (Bcl-2 and BAX) in the bone tissues of rats with chronic fluorosis." (PMID 34276389, 2021).
encephalitis (4 papers, 2017 to 2023). An acute inflammatory process affecting the brain parenchyma. "In post-mortem brains from HIV-1 patients with encephalitis, levels of autophagy proteins such as Beclin 1, ATG5, ATG7, and LC3-II were significantly increased, as compared to the brains from HIV-1 positive patients without HIV-1 encephalitis or uninfected controls." (PMID 33669846, 2021). "Notably, several key autophagic factors, such as BECN1, ATG5, ATG7, and LC3-II, were found to be elevated in the postmortem brains of HIV-1 encephalitis patients compared to HIV-1 patients without encephalitis." (PMID 37445802, 2023).
epilepsy (4 papers, 2022 to 2024). A brain disorder characterized by episodes of abnormally increased neuronal discharge resulting in transient episodes of sensory or motor neurological dysfunction, or psychic dysfunction. "Induction of autophagy and autophagy-related proteins like Atg7, LC3, and Beclin-1 by endothelial progenitor cells could be a novel therapeutic strategy in the management of epilepsy." (PMID 38006577, 2024). "Induction of autophagy and autophagy-related proteins like Atg7, LC3, and Beclin-1 might be an innovative therapeutic strategy in managing epilepsy." (PMID 37880579, 2023). "The induction of autophagy and autophagy-related proteins like Atg7, LC3, and Beclin-1 by endothelial progenitor cells could be a novel therapeutic strategy in the management of epilepsy." (PMID 37880579, 2023). "Additionally, another study revealed a sudden increasing in autophagy markers, namely beclin-1 and LC3II/LC3I in pilocarpine epilepsy model." (PMID 40217519, 2024).
fetal growth restriction (4 papers, 2020 to 2025). A fetus that does not grow beyond the 10th percentile of conventionally accepted weight for gestational age. "A number of studies have reported that typical markers of autophagy, LC3, and Beclin-1 expression, are significantly increased in placentas from pregnancies complicated by PE and intrauterine growth restriction (IUGR), suggesting that autophagy plays a key role in the pathogenesis of these diseases." (PMID 32626772, 2020).
gastric tumors (4 papers, 2012 to 2025). "BECN1 levels are significantly elevated in colorectal and gastric tumors compared to normal stomach and colon mucosal cells, with rates of 95% and 83%, respectively, suggesting that the high BECN1 expression may contribute to the development of both CRC and gastric tumors." (PMID 40723786, 2025).
gastrointestinal stromal tumor (4 papers, 2020 to 2022). "It is noted that miR-30a targeted Beclin-1 to inactivate autophagy in gastrointestinal stromal tumor cells." (PMID 36522638, 2022).
Glucose intolerance (4 papers, 2018 to 2025). Glucose intolerance (GI) can be defined as dysglycemia that comprises both prediabetes and diabetes. "Surprisingly, via GTT, we found that, after HFD feeding, the autophagy-hyperactive Becn1FA/+ or Becn1FA/FA mice have exacerbated glucose intolerance compared to WT mice, which is similar to findings with the autophagy-deficient Becn1+/− KO mice." (PMID 29898399, 2018). "Lacking autophagy genes (Beclin-1, Atg 7) can cause metabolic abnormalities as glucose intolerance, fat buildup, muscle atrophy, and early mortality." (PMID 40028479, 2025). "Similarly, Becn1 heterozygous mice also show partially decreased autophagy activity in metabolic organs, and systemic glucose intolerance and insulin intolerance upon high-fat diet feeding, even though their body weight is comparable to that of wild-type mice." (PMID 35646940, 2022).
intervertebral disc degeneration (4 papers, 2017 to 2022). "We suggest that pharmacologically targeting autophagy or gene therapy for autophagy-related genes such as mTOR, LC3, Beclin-1, p62, or other ATG genes are potential therapeutic options for degenerative disc diseases." (PMID 36009290, 2022).
lipodystrophy (4 papers, 2022 to 2024). A congenital or acquired disorder characterized by abnormal loss or redistribution of the adipose tissue in the body. "It has been suggested that BECN1 was required for mitophagy completion, and suppressed mitophagy by BECN1 deficiency could cause aberrant mitochondria quality control in adipocyte to cause lipodystrophy and metabolic dysregulation." (PMID 35370938, 2022). "Specifically, we employ adipocyte-specific BECN1 KO (BaKO) mice, which exhibit lipodystrophy due to dysfunctional adipocytes." (PMID 38744820, 2024). "Additionally, mice with Becn1 deletion in adipocytes develop lipodystrophy and have elevated endoplasmic reticulum stress gene expression stimulating adipocyte apoptosis." (PMID 38652543, 2024).
lung squamous cell carcinoma (4 papers, 2013 to 2025). "In this study, our results revealed that TRIM29 can regulate autophagy of lung squamous cell carcinoma through the BECN1 gene." (PMID 32640423, 2020).
medulloblastoma (4 papers, 2018 to 2024). A malignant, invasive embryonal neoplasm arising from the cerebellum. "For medulloblastoma, MirR-30a inhibited autophagy by reducing beclin 1/ATG5 expression and was linked to increased cell death in a medulloblastoma cell line." (PMID 36197606, 2022). "miR-30a targets Beclin-1, which mediates autophagy, and inhibits autophagy by downregulating the expression of Beclin-1 in medulloblastoma." (PMID 38338839, 2024).